CST3 (cystatin C)
Diseases named in the same sentence as CST3 in open-access papers (continued):
Sharing a sentence is not in itself a finding about the gene and the disease.
acute kidney injury (continued). "Several biomarkers such as Cystatin C and neutrophil gelatinase-associated lipocalin have been suggested for the diagnosis, severity classification and most importantly, the modification of outcome in acute kidney injury." (PMID 26804946, 2016). "• In the ICU, urinary cystatin C is diagnostic of acute kidney injury." (PMID 20459852, 2010). "We employed the system to the concomitant analysis of clinical concentrations of Neutrophil Gelatinase-Associated Lipocalin (NGAL) and Cystatin C in serum, two acute kidney injury (AKI) biomarkers." (PMID 33371213, 2020). "There is a controversy regarding accuracy of neutrophil gelatinase-associated lipocalin (NGAL) and Cystatin C in early detection of acute kidney injury (AKI)." (PMID 29503827, 2018). "Neutrophil gelatinase-associated lipocalin (NGAL), cystatin C (Cys-C), and soluble triggering receptor expressed on myeloid cells-1 (sTREM-1) are novel diagnostic biomarkers of acute kidney injury (AKI)." (PMID 25944130, 2015). "In clinical studies, free urinary cystatin C has been identified as a diagnostic marker for acute kidney injury (AKI) induced by sepsis, cardiac surgery or drug toxicity." (PMID 25310591, 2014). "Renal biomarkers such as NGAL, KIM-1, and cystatin C detect acute kidney injury significantly earlier than creatinine, and miR-122 holds strong potential as an early marker of hepatocellular injury." (PMID 41751199, 2026). "We found that heat stress increased plasma creatinine and cystatin C, in addition to urinary IGFBP7 × TIMP‐2, collectively indicating a potential risk for acute kidney injury." (PMID 39417775, 2025). "Further research is warranted to explore the correlation between HBP and hepcidin, respectively, and with possibly better biomarkers for acute kidney injury such as cystatin C. Cystatin C is a biomarker known to have advantages over serum-creatinine." (PMID 38696394, 2024). "This study aimed to assess plasma cystatin C (CysC) as a marker of acute kidney injury (AKI) in patients undergoing extracorporeal shock wave lithotripsy (ESWL)." (PMID 39301365, 2024). "Based on cystatin C concentration, acute renal failure can be diagnosed earlier than by determination of serum creatinine, and serum cystatin C is certainly a more sensitive marker of changes in GFR than serum creatinine." (PMID 38125620, 2024). "•Pb exposure is associated with proximal tubular dysfunction i.e. ↑ β2μG, α1μG & Cystatin-C, prior to clinical renal failure." (PMID 39717854, 2024). "It has recently been proposed that patients with renal failure have increased plasma cystatin C (CysC) levels." (PMID 39301365, 2024). "Pb-exposed individuals experience proximal tubular injury (KIM-1, NAG) and dysfunction (β2μG, α1μG, Cystatin-C) prior to obvious clinical renal failure." (PMID 39717854, 2024). "Beta-2-microglobulin (B2MG_HUMAN), and cystatin c (CYTC_HUMAN) showed elevated urinary levels in patients with acute renal failure." (PMID 37873871, 2023). "It was found that cystatin C is more sensitive to detect early acute kidney injury compared to serum creatinine (sCr), and cystatin C generally peaks within 24 h after contrast exposure." (PMID 37355592, 2023). "This patient’s kidney function was multiple typified by a marked elevation in serum creatinine/Cystatin C ratio (> 2 L/dL), potentially serving as a clue for the clinical diagnosis of pseudo-acute kidney injury engendered by urinary ascites." (PMID 37605159, 2023). "Although there are several renal failure markers for renal failure, including urine protein, lipocalin 2, and cystatin C, creatinine is granted as the primary one as an excellent clearance level in urine, interpretative simplicity, and high susceptibility." (PMID 35207080, 2022). "Other proteins in urine including KIM-1 and cystatin C have been related to renal failure and more specifically to tubular damage." (PMID 35757319, 2022).
acute kidney injury (continued). "CST3 was shown to be effective for estimating the glomerular filtration rate and is thus considered a potent biomarker for acute kidney injury." (PMID 36289608, 2022). "The primary outcomes were AKI incidence according to the Acute Kidney Injury Network (AKIN) criteria and blood biomarker of kidney injury, including neutrophil gelatinase-associated lipocalin (NGAL) and cystatin C levels within 48 h of surgery." (PMID 36431341, 2022). "Serum cystatin C has been evaluated as a more accurate and useful biomarker of acute kidney injury in the ELBW infant." (PMID 35433560, 2022). "Despite its known role in the assessment of renal function, cystatin C was reported as a potential marker of acute kidney injury." (PMID 35722493, 2022). "Frail patients were at a later stage of renal failure as estimated with both creatinine (p = 0.014) and cystatin C (p < 0.01)." (PMID 35743877, 2022). "A recent systematic review concluded that neutrophil gelatinase associated lipocalin (NGAL), cystatin C, and liver-type fatty acid binding protein (FABP-L) were the most promising for assessing postoperative renal failure after EVAR." (PMID 35054350, 2022). "Increases in acute kidney injury markers were observed after all experiments, but changes in urine albumin and cystatin C were highest after xylitol." (PMID 36338481, 2022). "The roles of NGAL and cystatin C in predicting acute kidney injury during COVID-19 are already the subject of clinical trials, the results of which should be awaited." (PMID 35054276, 2022). "Most of the current literature is based on predicting post-operative renal disease, with Cystatin C being the recognized early marker of renal failure." (PMID 35054350, 2022). "Serum Cystatin C performed better than serum creatinine in early prediction of moderate/severe acute kidney injury." (PMID 34871314, 2021). "CP-induced renal impairment was associated with an excessive increase in plasma and urinary output of cystatin C levels, which is reported to be a more sensitive marker for the diagnosis of acute kidney injury over creatinine and urea." (PMID 34727903, 2021). "Levels of five novel biomarkers, the functional marker serum Cystatin C and the damage markers urinary NGAL, cystatin C, β2-microglobulin and clusterin, were elevated in patients who developed moderate/severe acute kidney injury." (PMID 34871314, 2021). "Serum Cystatin C appears to be a promising novel biomarker in diagnosing acute kidney injury in the setting of hump-nosed pit viper envenoming." (PMID 34871314, 2021). "In clinical studies on acute kidney injury, an increase in serum and urine cystatin C levels is observed earlier than an increase in creatinine." (PMID 32784748, 2020). "Nor do these data allow us to test for differential associations between cystatin C and death after ARDS in patients with acute kidney injury from different causes." (PMID 32653023, 2020). "In a recent study of patients undergoing cardiopulmonary bypass surgery with cystatin C measured at 2, 4, 24, and 72 hours after surgery, serum cystatin C levels peaked significantly at 24 hours in the acute kidney injury (AKI) group compared to controls." (PMID 32411464, 2020). "The same was true for plasma Cystatin C. This was expected because Cystatin C is known as a marker for renal failure with higher levels of Cystatin C corresponding with more renal dysfunction." (PMID 32648717, 2020). "Many studies have highlighted the possible role of Cystatin C as an early marker of acute kidney injury and as more reliable as compared to serum creatinine." (PMID 29615540, 2018). "A meta-analysis of human studies demonstrated that patients with elevated cystatin C levels prior to the diagnosis of acute kidney injury have worse outcomes." (PMID 29312646, 2017). "This was observed for patients with renal failure (defined as a cystatin C-based glomerular filtration rate below 50 mL/min) or hepatic dysfunction (defined as prothrombin time < 50%)." (PMID 29180833, 2017).
acute kidney injury (continued). "This was observed for patients with renal failure (defined as a cystatin C-based glomerular filtration rate below 50 mL/min), liver failure (defined as prothrombin time <50%), or heart failure (defined as a NTproBNP >1000 pg/ml)." (PMID 28331622, 2017). "When considering GFR < 80 mL/min/1.73 m2 during the treatment for the definition of renal failure, AUC for cystatin C was 0.667, while the AUC for creatinine was higher (0.792)." (PMID 28078200, 2016). "In this study we tested the predictive accuracy of the baseline serum cystatin C levels as a tool to predict the occurrence of renal failure, defined as two different levels of GFR impairment, in patients receiving platinum-based chemotherapy." (PMID 28078200, 2016). "When considering GFR < 60 mL/min/1.73 m2 during the treatment for the definition of renal failure, AUC for cystatin C was 0.743, while the AUC for creatinine was 0.818." (PMID 28078200, 2016). "Univariate analysis of the mortality showed age, APACHE II, SOFA, Charlson Comorbidity Index, malignancy, acute renal failure, pulmonary infection, fungus infection, septic shock, cystatin c, and anion gap as potential predictors for one-year mortality." (PMID 28050557, 2016). "Cystatin C is a protease inhibitor freely filtrated by renal glomeruli and used as a good marker of renal failure." (PMID 24876663, 2014). "Several researchers reported cystatin C outperforms serum creatinine in the early diagnosis of acute kidney injury or its prognosis." (PMID 25215234, 2014). "Systematic reviews comparing several studies about diagnostic accuracy of serum cystatin C and serum creatinine for diagnosing renal failure found more studies favouring cystatin C, or describing cystatin C as equal, than those favouring creatinine." (PMID 24020893, 2013). "In detail, SDMA was found to correlate significantly with markers reflecting renal failure such as creatinine (r = 0.687, P < 0.001), cystatin C (r = 0.714, P < 0.001) or inversely with their glomerular filtration rates." (PMID 23935249, 2013). "One of the studies reported that serum cystatin C detected acute renal failure 1 to 2 days earlier than creatinine." (PMID 21067456, 2011). "In this study, we described p cytokines and cystatin C variations during and after hemodialysis in septic-shock patients with acute kidney injury (AKI)." (PMID 20546598, 2010). "Serum cystatin C and B2M were confirmed as easy and useful markers, better than serum creatinine, to detect acute kidney injury in critically ill children." (PMID 17519026, 2007). "In our experience, serum cystatin C and B2M were confirmed as simple and useful markers, better than serum Cr, to detect acute kidney injury in critically ill children." (PMID 17519026, 2007). "As previously shown in other groups of patients, in our experience serum cystatin C and B2M are better markers than serum Cr to detect acute kidney injury in critically ill children." (PMID 17519026, 2007). "We found that the capacities of cystatin C and B2M to detect acute kidney injury were better than that of serum Cr." (PMID 17519026, 2007). "The locus shared between creatinine and cystatin C overlapped BCKDK (lead variant: rs117766531 on chromosome 16), a gene involved in acidosis and glucocorticoids metabolism, and catabolic signals associated with renal failure." (PMID 39927731, 2025). "Furthermore, the device demonstrates satisfactory levels of analytical performance in terms of precision, sensitivity, and interference, indicating its potential for precise Cystatin-C quantification, particularly in renal-failure patients." (PMID 38248407, 2024). "Among the novel serum or urine biomarkers to predict acute kidney injury (AKI) after liver transplantation in patients with liver cirrhosis, neutrophil gelatinase-associated lipocalin (NGAL) along with cystatin C has been studied in the largest volume of studies." (PMID 37244919, 2023).
acute kidney injury (continued). "Many studies investigated urinary cystatin C in patients undergoing cardiac surgery, in the context of contrast administration, and they showed that it is an early diagnostic biomarker of acute kidney injury (AKI) in different settings, having elevated values 2 days before the AKI is installed." (PMID 35722493, 2022). "Cystatin C is a promising early marker of post-procedural acute kidney injury after EVAR." (PMID 35054350, 2022). "Similarly, cystatin C detects acute kidney injury early in cecal ligation and puncture-induced mice, and the combination of serum creatinine and serum cystatin C acts as a better biomarker for renal filtration." (PMID 33525404, 2021). "In addition, previous studies discovered that life cycle of serum cystatin C was half of that of SCr and increase of cystatin C level above 50% preceded SCr increase by 1.5 days to detect acute renal failure." (PMID 33478333, 2021). "In our study, we use KDIGO 2012 criteria for acute kidney injury, and using ROC curve analysis, we find that the plasma cystatin C level obtained in the first sample could predict severe AKI (stage 2 or 3 according to KDIGO 2012)." (PMID 32824680, 2020). "Changes of serum biomarkers of acute kidney injury, serum cystatin C, and serum creatinine." (PMID 33344994, 2019). "Cystatin C (CysC) is commonly used as a marker of renal failure in premature infants." (PMID 29082894, 2018). "Cystatin C is a valuable marker in the diagnosis of acute kidney injury in preterm infants." (PMID 29082894, 2018). "We also tested whether baseline cystatin C levels could predict time to renal failure in these patients." (PMID 28078200, 2016). "Cystatin C is an inhibitor of cysteine proteases which is expressed in all human nucleated cells, and has been shown to be upregulated in various pathological conditions including states of chronic and acute kidney injury." (PMID 26186708, 2015). "Serum cystatin C (CysC) is currently used in the prediction of acute kidney injury (AKI)." (PMID 25629773, 2015). "A further potential use of β2-microglobulin or Cystatin C may be as markers of improving kidney function in subjects with acute kidney injury requiring dialysis." (PMID 26629900, 2015). "We speculate that adiponectin may be trapped by C1q, as adiponectin is trapped by cystatin C in renal failure, thereby leading to an inactive adiponectin form, C1q-APN." (PMID 24883115, 2014). "Because of the association of renal dysfunction with CVD, it is unclear whether cystatin C is a direct marker of CVD or merely a marker for renal failure, which has implications for therapeutic intervention." (PMID 24478035, 2014). "Because of the association of renal dysfunction with cardiovascular disease, it is unclear whether cystatin C is a direct marker of cardiovascular disease or merely a marker for renal failure, which has implications for therapeutic intervention." (PMID 23630624, 2013). "This study analyzed the outcomes of coronary care unit (CCU) patients and evaluated several biomarkers of acute kidney injury (AKI), including neutrophil gelatinase-associated lipocalin (NGAL), interleukin-18 (IL-18) and cystatin C (CysC) on the first day of CCU admission." (PMID 22384218, 2012). "Serum RBP4 concentrations were also correlated with markers of renal failure, specifically increasing creatinine (r = 0.493, P < 0.001), urea (r = 0.389, P < 0.001), cystatin C (r = 0.381, P < 0.001) and decreasing glomerular filtration rate (GFR; r = -0.526, P < 0.001)." (PMID 20932285, 2010). "In this respect it is interesting to note that markers for acute renal failure that show a faster response, such as serum cystatin C, recently became available and these markers could be the better choice in acute models of kidney failure." (PMID 16784545, 2006). "Currently, the diagnosis and monitoring of acute kidney injury (AKI) primarily rely on indicators such as serum creatinine (Scr), urine output, and cystatin C (CysC)." (PMID 41332898, 2025).
acute kidney injury (continued). "KIM-1 and cystatin C were analyzed as biomarkers for detecting subclinical acute kidney injury (AKI) before serum creatinine levels rise, helping prevent irreversible kidney damage." (PMID 40426512, 2025). "Previous studies have demonstrated that the creatinine/cystatin C ratio (CCR) effectively predicts mortality in patients with acute kidney injury (AKI) undergoing renal replacement therapy and in cardiac surgery patients." (PMID 41383336, 2025). "Furthermore, the SCr/cystatin C (CysC) ratio (>2 L/dL) may serve as a clue for the clinical diagnosis of pseudo-acute kidney injury (pseudo-AKI) engendered by urinary ascites." (PMID 41261683, 2025). "In addition, serum cystatin-C and neutrophil gelatinase-associated lipocalin concentrations were significantly higher in calves with acute kidney injury than those without." (PMID 36670772, 2023). "While elevated blood levels of Cystatin C in individuals with COVID-19 are likely to indicate the existence of renal impairment, such as acute kidney injury (AKI), they may also be a sign of the excessive systemic inflammatory and pro-oxidant state that distinguishes patients with COVID-19." (PMID 36361485, 2022). "Functional-AKI was defined by the Acute Kidney Injury Network serum creatinine definition and alternatively by a ≥50% increase in serum cystatin C. Albuminuria was defined as albumin-creatinine ratio >30 mg/g." (PMID 28372541, 2017). "A wide variety of biomarkers, including creatinine, kidney enzymes, cystatin C, and injury molecules, have been developed for early detection of acute kidney injury (AKI)." (PMID 24864140, 2014). "In addition, cystatin C has been evaluated for the early diagnosis of acute kidney injury." (PMID 21773013, 2011). "Data analysis of renal and blood concentrations of KIM-1, cystatin C, GST, gamma-GT, Cre, and urea in control, S. nigra, GM + S. nigra groups were performed to detect the S. nigra extract ability to protect against acute kidney injury." (PMID 39861148, 2025). "Another group has also shown that NGAL and cystatin C may serve as markers of acute kidney injury (AKI) development in the course of COVID-19, with a distinguishing power similar to creatinine." (PMID 38673514, 2024). "Kashani K’s study demonstrated that NAGL was weaker than NephroCheck and urinary TIMP-2/IGFBP7, but stronger than plasma cystatin C and urine KIM-1 in predicting acute kidney injury." (PMID 35887790, 2022). "When renal failure was defined as GFR < 80 mL/min/1.73 m2, the best threshold of baseline cystatin C value according to Youden index (1.135) allowed dividing patients with baseline GFR > 80 mL into two groups." (PMID 28078200, 2016). "When renal failure was defined as GFR < 60 mL/min/1.73 m2, the best threshold of baseline cystatin C value according to Youden index (1.415) allowed to dividing patients with baseline GFR > 60 into two groups." (PMID 28078200, 2016). "Several studies have demonstrated the capacity of cystatin C to estimate GFR and that its ability to detect moderate acute kidney injury was better than that of Cr." (PMID 17519026, 2007). "Acute renal failure (increased serum cystatin C levels) was not different between WT and KO mice on day 2 of FAN." (PMID 38625739, 2024). "Acute renal failure (increased serum cystatin C levels) was not different between WT and Tg mice on day 2 of FAN, indicating that Cf48 overexpression did not affect AKI in this model." (PMID 38625739, 2024). "Biomarkers for postoperative renal failure after EVAR are extremely debated in the literature, with some having strong references (NGAL, cystatin C) and others having weaker data to support their use (retinol binding protein, IL-18, N-acetyle-b-D-glocosaminidase)." (PMID 35054350, 2022). "The role of serum cystatin C (Scys) for the detection of acute kidney injury (AKI) has not been fully discussed." (PMID 28112204, 2017).